RN7SKP235 (RN7SK pseudogene 235)
Gene: Miscellaneous RNA gene on chromosome 4 (145,035,132 to 145,035,436, forward strand). Ensembl gene ENSG00000222594.
Homologues: Orthologues: chimpanzee 7SK (99% identical), guinea pig 7SK (59% identical), mouse Gm55494 (56% identical), mouse Gm54935 (48% identical). Paralogues in human: RN7SKP128 (72% identical), RN7SKP255 (72% identical), RN7SKP246 (71% identical), RN7SKP9 (71% identical), RN7SKP146 (71% identical), RN7SKP199 (71% identical), RN7SKP93 (71% identical), RN7SKP95 (71% identical), RN7SKP224 (70% identical), RN7SKP273 (70% identical), RN7SKP50 (70% identical), RN7SKP71 (70% identical), and 284 more.